MTOR (mechanistic target of rapamycin kinase)
Diseases named in the same sentence as MTOR in open-access papers (continued):
Sharing a sentence is not in itself a finding about the gene and the disease.
tumor (continued). "While these results are somewhat limited by considerations of sample size and heterogeneity of patient treatment regimens, our findings are supportive of our model that tumor regressive processes in humans also involve stromal PI3K/Akt/mTOR pathway activation." (PMID 26098779, 2015). "In this paper, we focused on the study of antiproliferative effect of mTORC1 inhibitor rapamycin and an inhibitor of the mTOR kinase domain pp242 on tumor rodent E1A + cHa-Ras (ERas) cells." (PMID 26636543, 2015). "Although not conclusive, molecular mechanism linked to observed apoptotic resistance in this tumor type seems to involve the activation of the PI3K, Akt, and mTOR signaling pathway." (PMID 25726528, 2015). "GOLPH3 promotes cell transformation and tumor growth by activating mammalian target of rapamycin (mTOR-YB-1) signaling pathway." (PMID 28983350, 2015). "Positive PI3K, Akt, mTOR, and p70S6K1 immunostaining was predominantly observed in the cytoplasm or on the plasmalemma of tumor cells." (PMID 25788964, 2015). "Inhibitors of mTOR such as rapamycin, everolimus, and temsirolimus have all been shown to inhibit tumor cell proliferation in several cellular models." (PMID 25741318, 2015). "The mammalian target of rapamycin (mTOR), which is a central regulator of cell growth and cell apoptosis, contributes to tumor progression and drug resistance." (PMID 25654224, 2015). "In this study, we demonstrated that mTOR inhibitor, sirolimus, is able to suppress FLCN-deficient allograft and xenograft tumor growth." (PMID 26418749, 2015). "In conclusion, we have demonstrated a crucial role for mLST8-mediated upregulation of the mTOR pathway in promoting tumor progression." (PMID 25906254, 2015). "The transcriptional profile confirmed the clinical suspicion of highly upregulated macro-autophagy and dysfunctional pathway activity in c-MET, MAPK, TSC2 and S100A9, and downregulation of mTOR, as previously reported relevant for this type of tumor." (PMID 26654961, 2015). "The mTOR target 4EBP1 was initially considered a tumour suppressor gene, as a result of its role in negatively regulating the translational machinery through binding to EIF4E." (PMID 26698305, 2015). "VHL inactivation is the most established cause of ccRCC, but there are several other factors involved in pathogenesis of tumor type exemplified by mutations in KNG1 and MT1A genes, as well as PI3K/AKT/mTOR signaling pathway factors (MTOR, PTEN, PIK3CA)." (PMID 26169495, 2015). "The mTOR catalytic kinase inhibitors that target both mTORC1 and mTORC2 or dual mTOR/PI3K inhibitors are predicted to show greater clinical efficacy than rapalogs for the treatment of LKB1 mutant tumours." (PMID 26196184, 2015). "In summary, inhibition of the PI3K/mTor pathway in tumor cell lines with ligand-independent Wnt activity further increases canonical Wnt signaling." (PMID 26205886, 2015). "Based on these findings, we conclude that combined GLI1/2 and PI3K/mTOR inhibition is a promising novel therapeutic approach for synergistic apoptosis induction and tumor growth reduction in RMS." (PMID 25749378, 2015). "The tumor as well as the cultured cells stained positive with our panel of phospho-mTOR-target-antibodies." (PMID 25993328, 2015). "A key downstream effector of PI3K/Akt is mTOR, a kinase that increases cellular energy consumption to drive anabolic processes including protein translation and lipid synthesis to support tumor cell proliferation." (PMID 26637440, 2015). "In this study, we addressed the role of mLST8, a requisite component of mTOR complexes, in tumor progression." (PMID 25906254, 2015). "Inhibition of mTOR activity leads to tumor regression in a KS mouse model, whereas mTOR overexpression was sufficient to render endothelial cell oncogenic when injected in mice." (PMID 25805993, 2015).
tumor (continued). "Rapamycin suppresses tumor cell growth/proliferation and motility, and induces apoptosis of tumor cells under certain conditions by inhibiting the kinase activity of mTOR." (PMID 25762619, 2015). "The fact that the better anti- tumor effect observed in rapamycin-treated mice was accompanied with a greater decrease in the phosphorylation status of P70S6K suggests a more effective mTOR pathway inhibition." (PMID 26397134, 2015). "Staining of mTOR in the tumor center correlated with p-mTOR (r = 0.195, p = 0.028), and there was a positive association MMP2 with MMP9 at the invasive front (r = 0.214, p = 0.015)." (PMID 26652716, 2015). "Emerging preclinical studies of mTOR active site inhibitors demonstrate variable control of tumor growth." (PMID 26295809, 2015). "The levels of phospho-Akt (p-Akt), phosphor-mTOR (p-mTOR) and phospho-p70S6 (p-p70S6), all of which are mTOR substrates, in the two tumor cell lines were measured." (PMID 26338671, 2015). "GSEA analysis our RPPA results show that CSC stemness pathways and PI3K/mTOR pathways were inhibited, while proapoptosis and tumor suppressive genes were induced by ABT-263." (PMID 26317542, 2015). "Pretreatment tumour specimens were available from 57 of these patients for assessment of MTOR mRNA expression." (PMID 26639561, 2015). "Pharmacogenomic profiling of mTOR-p70S6K pathway shows that the protein synthetic machinery is overexpressed and activated during tumor progression." (PMID 26447757, 2015). "PI3K/AKT-mediated activation of the downstream target mTOR results in cell proliferation and survival by regulating the translation of proteins involved in tumor progression." (PMID 26299806, 2015). "Our protein expression data revealed an inhibitory effect of PROG (80 μM) alone and in combination with TMZ on the expression of both pAkt (Ser437) and mTOR following 3 days of repeated exposure in both tumor cell lines." (PMID 26110872, 2015). "Nowadays, the chance to have recourse to immunosuppressants such as mycophenolate and mTOR inhibitors has allowed a large number of kidney-transplanted patients who develop a tumor to recover by maintaining the function of the transplanted organ." (PMID 26185750, 2015). "In RMS, concomitant inhibition of the RAS/MEK/ERK and PI3K/AKT/mTOR pathways has recently been demonstrated in two independent studies to synergistically trigger apoptosis and to inhibit tumor growth in vivo." (PMID 26157704, 2015). "As an important regulator of cell growth and proliferation, the mTOR has been the subject of intense investigation for its role in tumor development and progression." (PMID 26176608, 2015). "Using animal models we have also concluded that the administration of mTOR-pathway inhibitor sirolimus offers potential against these highly malignant tumours." (PMID 26569621, 2015). "Several studies have demonstrated the therapeutic efficacy of mTOR inhibitors on suppressing tumor growth in a number of solid tumors on human subcutaneous growing xenografts and in many phase I–III clinical studies." (PMID 26397134, 2015). "The complexity of miR-100 function in the tumor microenvironment underscores this argument by its potential for inhibiting mTOR expression which is required for proliferation of Apc-deficient tumors in mouse models." (PMID 26132860, 2015). "The Akt/ mTOR pathway modulates cellular function in response to extracellular signals and can lead to tumor initiation and progression." (PMID 26502919, 2015). "Overactivated mTOR function is often observed in a variety of tumors promoting protein synthesis and tumor growth." (PMID 25792980, 2015). "Only for intestinal type tumors, there was a correlation of mTOR with MMP9 expression both in the tumor center (r = 0.251, p = 0.020) and at the invasive front (r = 0.254, p = 0.018)." (PMID 26652716, 2015).
tumor (continued). "miR-218 has been shown to be epigenetically (DNA hypermethylation) silenced in OSCC tissue specimens and to have a tumor suppressive function by regulating the expression of rapamycin-insensitive component of mTOR, Rictor." (PMID 26504785, 2015). "Collectively, these data suggested that combining metformin with cisplatin, rapamycin, or both effectively decreased tumor burden by suppressing the pivotal AMPK/mTOR/S6 signaling axis." (PMID 25909163, 2015). "Here we used gene transcript profiling to gain a deeper understanding of the role of FBXW7 in tumor development and to determine the influence of mTOR inhibition by rapamycin on tumor transcriptome and biological functions." (PMID 26575021, 2015). "Taken together, XBP1 is up-regulated and has a pro-tumor effect in OS with activation of PI3K/mTOR signaling." (PMID 26633383, 2015). "Expression of the FK506 binding proteins FKBP4, FKBP6, and FKBP9, immunophilins known to interact with mTOR, was upregulated in DC-tumor fusions 5.3-, 6.7-, and 28-fold." (PMID 26605345, 2015). "Western blot analysis performed on the expression profiles of the MTOR signal cascade in the tumor adjacent tissues revealed that the treated group expressed a lower level of MTOR/EIF4EBP1/YY1/MYC/SLC2A1 signaling than the untreated group." (PMID 25909713, 2015). "In this study we evaluated the antitumor activity of the allosteric mTORC1 inhibitor, rapamycin and of the ATP-competitive mTOR inhibitor WYE-354 on preclinical xenograft GBC tumor models." (PMID 26397134, 2015). "It has been well-documented that mTOR dysfunction can transform normal cells into tumor-like cells and switch the energy metabolism from mitochondria-centered oxidative phosphorylation to aerobic glycolysis." (PMID 25807077, 2015). "This was further reflected in the constitutive activation of the mTOR signal transduction pathway in the tumor." (PMID 26510912, 2015). "Direct repression of mTOR by the miR-101 tumor suppressor was reported in OS, and inhibition of cell proliferation and apoptosis were mediated through suppression of mTOR." (PMID 26380245, 2015). "These drugs have been shown to inhibit HIF1A, and PI3K and mTOR are here suggested as potential targets in cases with tumor necrosis." (PMID 26485755, 2015). "Rapamycin treatment of cultured human adipocytes resulted in down-regulation of gene expression of SREBF1 suggesting that the tumor promoting effects of the FBXW7-SREBF axis is dependent on mTOR." (PMID 26575021, 2015). "Consecutive patients with diverse tumor types and PIK3CA mutation were treated whenever possible with agents targeting the PI3K/AKT/mTOR pathway." (PMID 26404261, 2015). "This demonstrated that BBN-induced lesions were able to recapitulate the association between altered glycosylation and an activated PI3K/Akt/mTOR pathway previously observed in advanced stage human tumours." (PMID 26569621, 2015). "The deregulation of both RAF/MAPK and AKT/MTOR signaling pathways is thought to play a critical role in carcinogenesis and tumor progression in NSCLC." (PMID 25706985, 2015). "The expression of p-mTOR was higher in the tumor center than at the invasive front, with a similar trend for mTOR." (PMID 26652716, 2015). "There are several clinically approved drugs that target mTOR, notably temsirolimus, which has been reported to boost the efficacy of tumor vaccines." (PMID 26343197, 2015). "Insulin plays a central role in metabolic regulation and its signaling component mTOR also plays important roles in tumor growth." (PMID 25792980, 2015). "Supporting this in vivo observation, increased expression of PRL-3 during tumour progression in the MMTV-PyMT spontaneous transgenic mouse model was closely mirrored by an increase in both mTOR and 4E-BP1 phosphorylation levels." (PMID 26597054, 2015). "Primary tissue slices of 400 μm were cultured in the presence of rapamycin, showing that such a culture method preserves the tumor AKT/mTOR pathway activity." (PMID 26133490, 2015).
tumor (continued). "For instance, tumours with activating mTOR mutations or inactivating TSC1 and NF2 mutations have both been shown to be sensitive to the mTOR inhibitor everolimus." (PMID 26404381, 2015). "We also evaluate cellular localization of mTOR protein in MM cell lines and in primary tumour cells." (PMID 26097872, 2015). "In these tumor types a high expression of SERPINE1 protects cells from chemotherapy-induced apoptosis and associates with the activation of the PI3K/AKT/mTOR signaling pathway." (PMID 26359694, 2015). "The engrafted mice were treated with various combinations of endocrine therapies and the mTOR inhibitor everolimus, the impact of which on tumor proliferation was evaluated by Ki67 staining." (PMID 26637281, 2015). "Both inhibitors effectively decrease mTOR activity, leading to a remarkable decrease in tumor burden and prolonged survival in immunocompromised mice." (PMID 26022660, 2015). "Targeting the PI3K/AKT/mTOR pathway has been shown to increase anti-tumor activity of inhibiting EGFR." (PMID 25928246, 2015). "Recent studies have indicated that UA inhibits tumor cell growth through the inhibition of the Akt/mTOR signaling pathway." (PMID 25689721, 2015). "For instance, our group has used the Kras; Pten mouse model, in which tumours have high levels of mTOR (mammalian target of rapamycin) signalling, to test the efficacy of an mTOR inhibitor." (PMID 26438692, 2015). "Especially the MEK inhibitor AZD6244 and the dual PI3K/mTOR inhibitor NVP-BEZ235 demonstrated synergistic effects in several in vitro studies investigating various tumor entities." (PMID 26498922, 2015). "This treatment durability after withdrawal of therapy and survival effect of mTOR inhibition relative to MEK inhibition appeared to be more pronounced in immunogenic MOC1 tumor bearing mice compared to MOC2 tumor bearing mice." (PMID 26506415, 2015). "In malignancies, the mTOR pathway is often hyperactivated, and the use of mTOR inhibitors can slow the proliferation of malignant cells and interfere with angiogenesis needed for tumor growth 7,9." (PMID 26108799, 2015). "We examined the anti-tumor activities of three mTOR inhibitors including everolimus, temsirolimus and rapamycin against 7 SCLC cell lines by MTS assay." (PMID 25884680, 2015). "Clinicopathologically, the positivity for p-mTOR was correlated with the existence of metastasis (p = 0.003), tumor necrosis (p = 0.0007) and >10 % MIB-1 labeling index (LI) (p = 0.0038)." (PMID 26502919, 2015). "Considering the intricacy of tumor formation, it is impossible that the mTOR is the only one ascribed to the ESCC." (PMID 26357655, 2015). "For example, combining the mTOR inhibitor rapamycin with the cytotoxic gemcitabine led to cell cycle arrest in vitro and this combination was recently confirmed to strongly inhibit tumor growth in vivo by an independent group." (PMID 26576131, 2015). "These clinical results implied a possible relationship between PRL-3 expression levels and mTOR activity in tumour tissues." (PMID 26597054, 2015). "There is evidence in human and mouse tumor cells that mTOR inhibition activates ERK phosphorylation." (PMID 26121028, 2015). "To investigate mechanisms to explain the differences in response to therapy between MEK and mTOR inhibition in MOC tumor bearing mice, we wished to validate the on-target effects of PD901 and rapamycin treatment in vivo." (PMID 26506415, 2015). "Our observations that rapamycin dramatically blocked the tumor metastasis induced by silencing FBXW7 both in vitro and in vivo provided us a therapeutic option by targeting mTOR in FBXW7 deficient patients in clinical practice." (PMID 25749036, 2015). "Since there are no known mutations in the PI3K/mTOR signaling cascade in A549 cells, it is likely, that the different tumor entity is the main reason for the different sensitivity towards dual PI3K/mTOR inhibition." (PMID 26498922, 2015).
tumor (continued). "Nevertheless, vessel development and tumor growth proceeds in humans treated with rapalog drugs, prompting the investigation of agents that inhibit mTOR in both complexes." (PMID 26295809, 2015). "For instance, angiogenesis relies on vascular endothelial growth factor expression and signalling in supportive tumour vessel structures, which are dependent on the mTOR pathway." (PMID 25699174, 2015). "Conversely, autophagy is induced upon blockade of mTOR or factors upstream of mTOR, transiently supporting cell survival and reducing the anti-tumor impact of therapeutic inhibitors of HER2, type I PI3Ks, and mTOR." (PMID 26637440, 2015). "MiR-125b inhibits the PI3K/AKT pathway through downregulation of mRNA and protein PIK3CD via 3′-UTR binding, which is conducive to protein kinase A (AKT) and mTOR phosphorylation, inducing tumor growth volume inhibition." (PMID 26057746, 2015). "AZD8055 is a first-in-class orally available, potent and specific inhibitor of mTOR kinase activity, and shows a promise for suppressing tumor growth." (PMID 26421002, 2015). "We have shown that mTOR inhibitors dramatically block tumour angiogenesis, which leads to substantially reduced tumour growth in animal models." (PMID 25699174, 2015). "Paclitaxel from the PEM and its diffusion into the tumor inhibited angiogenesis, which involved suppression of mammalian target of rapamycin (mTOR) through regulation of hypoxia inducible factor (HIF-1) and increased apoptosis." (PMID 25983747, 2015). "Accumulating evidence indicates that the tuberous sclerosis complex 1 (TSC1), a tumor suppressor that acts by inhibiting mTOR signaling, plays an important role in the immune system." (PMID 26000908, 2015). "Our Annexin A1 depletion in TNBC cell lines further suggests its tumorigenic role by promoting tumor cell migration through increased mTOR signaling." (PMID 26000884, 2015). "A second class of agents includes temsirolimus and everolimus, which both exhibit anti-tumor effects through inhibition of the mTOR pathway." (PMID 25885920, 2015). "Rapa and newer generation mTOR inhibitors have limited clinical activity, except in certain tumor types with heavy dependence on mTOR." (PMID 26375670, 2015). "These mTOR inhibitors are potentially promising for the treatment of multiple TSC-related tumor types, including renal angiomyolipomas, subependymal giant cell astrocytomas and lymphangioleiomyomatosis." (PMID 25574245, 2015). "Our study demonstrated the high therapeutic efficacy of two mTOR inhibitors on suppressing tumor growth on subcutaneous GBC tumor models." (PMID 26397134, 2015). "Similar treatment efficacy was also reported in the PTEN genetically engineered mouse model in that the mTOR inhibitor rapamycin treatment led to complete regression of SGT tumor growth." (PMID 25909167, 2015). "We have found that both a reduction in dietary protein and intermittent fasting slow tumor growth rate, but have distinguishable effects on mTOR signaling both in the tumor and the somatic tissues of a tumor-bearing mouse." (PMID 26378060, 2015). "The downstream effects of PRL-3 were maintained even under conditions of environmental stress, suggesting that PRL-3 provides a strategic survival advantage to tumour cells via its effects on mTOR." (PMID 26597054, 2015). "Recombinant NY-ESO-1 intranodal injection before sirolimus indicated superior anti-tumor efficacy of mTOR inhibition through promoting CD8+ T-cell memory responses." (PMID 25865224, 2015). "Rapamycin known as an mTOR activation inhibitor is clinically used for its anti-tumor effect and immunomodulation." (PMID 25884175, 2015). "Activation of the mammalian target of rapamycin (mTOR) signalling contributes to the pathogenesis of many tumor types." (PMID 26078352, 2015).